MIR4657 (microRNA 4657)
Synonyms: hsa-mir-4657; mir-4657
Gene: MicroRNA gene on chromosome 7 (44,881,748 to 44,881,800, reverse strand). Ensembl gene ENSG00000284261.
Homologues: Orthologues: mouse Gm22123 (100% identical).